GLI1 (GLI family zinc finger 1)
Diseases named in the same sentence as GLI1 in open-access papers (continued):
Sharing a sentence is not in itself a finding about the gene and the disease.
cancer (continued). "IL25 inhibited phosphorylation of AMPK and promoted GLI1 accumulation to maintain cancer stem cells." (PMID 35359953, 2022). "Studies have confirmed that endogenous ADAR1 can directly bind to the mRNA of glioma-associated oncogene 1 (GLI1) and then promote its transcriptional activity by inducing RNA editing of GLI1, and the edited GLI1 is involved in a variety of cancers." (PMID 36497204, 2022). "Our results indicate that the Hh-GLI1 signaling pathway regulates proliferation and glycolytic metabolism in cancer, which can provide novel perspectives for TNBC treatment." (PMID 36046646, 2022). "To determine the effect of GLI1 silencing on the generation of lactate, the major metabolite in cancer cells, we quantitatively analyzed lactate levels in the media of MDA-MB-231 cells using HPLC." (PMID 36046646, 2022). "On the other hand, WNT signaling has been reported to induce GLI1 expression, GLI1 mRNA stabilization and GLI1 transcriptional activity in several cancer cell types." (PMID 35908024, 2022). "The identification of GLI1 as a key transcriptional regulator for cancer cell proliferation and cell death pathway highlights its promise as a therapeutic target." (PMID 36046646, 2022). "Based on these findings, small molecule inhibition of DYRK1B was proposed to be a promising approach to target GLI1-dependent cancers resistant to SMO inhibitors." (PMID 35163655, 2022). "The Hh-GLI1 signaling pathway is usually turned off in normal cells; however, abnormal activation has been reported in several cancers 27, making it an attractive therapeutic target." (PMID 36046646, 2022). "In B-cell ALL, cancer stem cells that were treated with a Smo inhibitor showed decreased self-renewal potential, a result mirrored by the subset of GLI1 rich T-cells when they were treated with either a GLI or SMO inhibitor." (PMID 36091167, 2022). "summarized the known target genes of GLI1 in human cancers, including components of the Hh signaling pathway (PTCH, SHH, and SMO)." (PMID 35785194, 2022). "In the present study, we investigated the role of the Hh-GLI1 signaling pathway in cancer proliferation and glucose metabolism in TNBC." (PMID 36046646, 2022). "Studies had showed that Gli1 was abnormally expressed in a variety of tumors and suppression of Gli1 inhibited proliferation and migration of cancer cell." (PMID 36246980, 2022). "In this way, the downstream mechanisms of GLI1 activation have been related to aberrant HH signaling in several human cancer, including OSCC." (PMID 36552049, 2022). "CD200 + CD45 cancer cells have been determined to be a CSC population in BCC that expresses high levels of Gli1 and depends on Gli1 for survival." (PMID 36517618, 2022). "Targeting DYRK1B is also suggested as a novel alternative strategy to overcome the drug resistance in GLI1-dependent cancer." (PMID 35163655, 2022). "The SMO, Gli1, and Shh played a crucial role in the Hedgehog signaling pathway on the progress of cancer." (PMID 36246980, 2022). "Accordingly, GLI1 inhibitors are promising as anti-cancer drugs due to their role in targeting multiple oncogenic signaling pathways." (PMID 36552049, 2022). "Recently, the application of GLI1 to overcome anti-SMO resistance in several cancers has spurred great interest." (PMID 33637972, 2021). "Conversely, the knockdown of GLI1 or TAP1 via an RNAi approach or the inhibition of GLI1/GLI2 function with GANT61 markedly improved the subpopulations’ sensitivity to all three cancer therapeutics." (PMID 34638233, 2021). "This paracrine signal activates GLI-Kruppel family member GLI1 (Gli1) signalling in neighboring cancer cells and promotes their metastasis." (PMID 33674758, 2021). "The HH/GLI1 pathway promotes cancer growth, stem cell self-renewal and metastatic behavior in advanced CRC." (PMID 34490089, 2021).
cancer (continued). "ADAR1 promotes malignant regeneration of MM by mediating the recoding of the self-renewal agonist GLI1, which activates the Hh pathway and promotes the production of cancer stem cells." (PMID 34976013, 2021). "The involvement of LncRNA SOX2‐overlapping transcript (SOX2‐OT), SOX2, and GLI‐1 transcription factors in cancer has been well documented." (PMID 33433063, 2021). "It reduces Gli1 gene expression, and in gastric cancer cells, it decreases cancer stem-like properties." (PMID 34336089, 2021). "Genistein can transform typical cellular characteristics in stem cells of cancer by inhibiting signaling Gli1-related pathways." (PMID 34336089, 2021). "Taken together, GLI1/2 mediates mTOR-induced PD-L1 expression to promote immune evasion of cancer cells, as well as promotes chemoresistance." (PMID 34572373, 2021). "All of these pathways drive GLI1 expression, defining GLI1 as a cancer stem cell marker in multiple types of cancer, including colorectal." (PMID 34113570, 2021). "Transcription factor SOX-9, a novel cancer stem cell marker, expression was shown to be regulated by GLI1 to promote CSC features in PDAC PANC-1 cells." (PMID 34572373, 2021). "We evaluated GLI1 protein expression in LMS tissue by immunohistochemistry and demonstrated that the expression of GLI1 protein in LMS cancer cells is consistent with that of a previous study indicating the expression of GLI in LMS tissue." (PMID 33906647, 2021). "It has been previously reported that overexpressed GLI‐1 is associated with cisplatin resistance, the co‐expressed GLI‐1/SOX2 transcript axis is related to TKI‐erlotinib, and taxane‐gemcitabine‐drug cancer resistance in prostate and lung cancer." (PMID 33433063, 2021). "As such, by targeting the downstream effector (GLI1) rather than upstream activators, we can effectively inhibit the oncogenesis driven by aberrant GLI1 activation, and promote cancer-specific DNA damage." (PMID 34113570, 2021). "It has also been demonstrated that Rack1 promotes non‐small‐cell lung cancer (NSCLC) tumorigenicity by activating Smoothened to mediate Gli1‐dependent transcription in cancer cells." (PMID 34480519, 2021). "For this reason, GLI1 is a significant therapeutic target for the treatment of multiple cancer types." (PMID 34113570, 2021). "The SOX2 gene has been shown to possess transcriptional ability to regulate the expression of the GLI‐1 gene, participating as a member of the Sonic Hedgehog (Sh) pathway in cancer therapy resistance mechanisms of lung neoplasms." (PMID 33433063, 2021). "GLI1 can initiate cancer cell EMT by increasing expression of SNAIL1 and vimentin but decreasing E-cadherin, causing β-catenin to migrate into the nucleus and act as a transcription factor, inducing cell transformation." (PMID 34113570, 2021). "The RAF/MEK/ERK signaling cascade upregulates Gli1 expression/activation to promote cancer cell, proliferation, survival, invasion, and drug resistance." (PMID 34970481, 2021). "The induction of sonic hedgehog (SHH) by KRAS in cancer cells triggers the expression of the transcription factor GLI1 in fibroblasts." (PMID 33691728, 2021). "GLI1 is overexpressed in BCSCs characterized by CD44+/CD24- phenotype compared to other cancer cells and is important for EMT and metastatic progression." (PMID 34889737, 2021). "GLI1 was the most widely reported member involved in the GLI zinc finger family, and it is well acknowledged that GLI1 promotes malignant progression in cancers by regulating the Hedgehog signaling pathway." (PMID 33506047, 2021). "In western blot analyses, 61.1% (22/36) of cancer samples illustrated higher Gli1 expression level than in paired normal tissue samples." (PMID 31931858, 2020). "In light of these new findings, this review summarizes the modes of HH signaling, the structures and properties of the three GLI1 isoforms, and the role of aberrant HH activation in cancer." (PMID 32957513, 2020).
cancer (continued). "GLI1-upregulating agents lead to G1 and sub-G1 phase arrest and apoptosis in different kinds of cancers." (PMID 33218150, 2020). "As a result, our findings demonstrated Gli1 activation in cancer tissue samples, with significant correlations to EMT and AKT pathway markers." (PMID 31931858, 2020). "Although Gli1 expression has been studied in many human cancers, its role as a prognostic indicator and its functional significance in determining the stemness of GA cells warrants further investigation." (PMID 32430068, 2020). "tGLI1 expression distinctly differs from GLI1 and GLI1ΔN because both of these isoforms are expressed in both normal and cancer cells." (PMID 32957513, 2020). "A series of biochemical and genetic assays elucidates a mechanism by which BRAFV600E mutant cancers circumvent the efficacy of 5-FU induced DNA damage through a previously undescribed GLI1-mediated transcription of the DNA damage-sensing protein NBS1." (PMID 32185127, 2020). "By maintaining only one metabolic pathway, cancer cells with a GLI1+/IFT20+ signature offer a metabolic vulnerability that we would be wise to exploit." (PMID 32194829, 2020). "Dispatched is essential for the release of Hedgehog proteins from the producing cells and Hedgehog-GLI1 was reported to contribute to the survival of cancer cells by promoting transcription of AKT genes by its direct binding in the AKT promoter region." (PMID 32962246, 2020). "Gli1 was upregulated in GA tissues and cancer cells and correlated with poor prognosis in GA patients." (PMID 32430068, 2020). "The result showed that Gli1 related with cancer stemness proteins, CD44, LSD1, and Sox9 (all P < 0.05)." (PMID 32430068, 2020). "Elevated levels of Wnt signaling components in response to hedgehog pathway abnormalities and GLI1 expression are reported in cancer where elevated expression of GLI1 led to the accumulation of β-catenin in nucleus." (PMID 32922954, 2020). "In this study, Gli1 proved to be a molecular marker for cancer stemness and a prognostic indicator of GA." (PMID 32430068, 2020). "Reduced expression of Gli1 downregulated the protein levels of cancer stemness biomarkers while also decreasing cell clonogenic potential in GA cells." (PMID 32430068, 2020). "Together with its broad pan-cancer pejorative prognostic value distinct from that of TGFB/GLI1/2/EMT/Stemness, suggests a potential therapeutic benefit for the combination of cytostatic drugs together with anti TGF-β/GLI inhibitors." (PMID 32879407, 2020). "To identify the role of Gli1 in cancer stemness of GA, we studied Gli1 and stemness-related protein expression in GA." (PMID 32430068, 2020). "Our study demonstrated that Gli1 expression correlates with expression of cancer stemness-related proteins." (PMID 32430068, 2020). "To further understand the interaction between Gli1 and cancer stemness in GA cells, we blocked Gli1 expression using Gli1 inhibitor in MKN28 and MKN74 cells." (PMID 32430068, 2020). "Among them, six transcription factors regulating the cancer stem cell-associated genes were verified by the reported literatures (marked with deep red), including NR4A1, FOS, KLF-4, GLI1, NFATC1 and JUN." (PMID 32242101, 2020). "Hh/GLI1 signaling is a promising target for cancer therapies, as the pathway controls major biological hallmarks of cancer, including proliferation, metastasis, survival, self-renewal and angiogenesis." (PMID 33170154, 2020). "NKX2-2 is one of the downstream target genes of GLI1 in the Sonic hedgehog (Shh) signaling pathway, and impairment of this pathway can result in both birth defects and cancer." (PMID 33179733, 2020).
cancer (continued). "We determined changes in gene expression in the VCR-resistant cells compared with parental cells using an 86-gene cancer drug resistance array that included GLI1 and tested the effect of GLI1 inhibition with GANT61 or GLI1 siRNA on VCR resistance." (PMID 32493277, 2020). "Expression of FOXM1 correlates directly with the expression of patched-1 (PTCH1), smoothened (SMO) and GLI1 in various cancers." (PMID 33680951, 2020). "The Sonic hedgehog (SHH) signaling pathway, strongly involved in the development of many cancers, regulate transcription via the transcriptional factors Gli1-3." (PMID 33228057, 2020). "Gli1 and Gli2 inhibitor include GANT 61 and Arsenic Trioxide that have shown potent inhibition of Gli1 and Gli2 in many cancer cell lines, one of these is GC cells." (PMID 32430068, 2020). "Although extensive experimental evidence exists for a pro-tumorigenic and pro-metastatic role of GLI1, efficacy of HH inhibitors is restricted to a handful of cancers with genetic activation of upstream components of the pathway." (PMID 32879407, 2020). "Generally, GLI1 acts mainly transcriptional activation in cancer cells, whereas GLI2 requires N-terminal processing for full activation." (PMID 32354204, 2020). "GLIΔN appears to function similarly to the wild-type GLI1, albeit with weaker gene activation, and is expressed at equal or lower levels in cancers compared to normal tissues." (PMID 32957513, 2020). "We found higher expression of Patched1 (PTCH1), Shh, Sufu, Smo, Gli1, Gli2 and Gli3 both at mRNA and protein levels than adherent cancer cells." (PMID 32575925, 2020). "Forced expression of miR-361-3p is reported to limit cancer cell proliferation by targeting GLI-1/3 and sonic hedgehog signaling." (PMID 33489917, 2020). "An example is the documented fusion of MALAT1 to GLI1, which enhances GLI1 expression, and thus hedgehog signaling in different types of cancer." (PMID 33329688, 2020). "Except for those 14 cancer classification marker genes, there were significant differences in the expression of three genes: GLI1 (GLI family zinc finger 1), KRT19 (Keratin 19), and VEGFA." (PMID 33692941, 2020). "Increased expression of miR-324-5p has significant inhibitory effect on SMO and GLi-1 and limits cancer stemness of cells." (PMID 33489917, 2020). "During pancreatic carcinogenesis, MCPH7 is responsible for the depression of GLI1, which is a crucial step in activating Hh signaling in cancer cells." (PMID 32121580, 2020). "Gli2 was localized in the cytoplasm and nucleus of cancer cells and 57% of patients showed a high level of Gli1 expression." (PMID 31417657, 2019). "In this model, loss of GLI1 impaired KRAS-induced pancreatic carcinogenesis, revealing a targetable KRAS-driven mechanism underlying the crosstalk between cancer cells and the pancreatic stromal compartment." (PMID 31847096, 2019). "Based on the GLI1 expression data, H1299 and A549 cancer cell lines and MRC-9 normal cells were chosen for the present study." (PMID 31783569, 2019). "Elucidating the combinatorial protein-protein interactions that regulate GLI1 expression will provide new therapeutic approaches to GLI1 induced cancers overcoming the shortfall of upstream inhibitors whose efficacy is limited by non-canonical signaling." (PMID 31085420, 2019). "Whilst IL-24 as a cancer therapeutic is accepted, its role on HH signaling and/or its downstream target GLI1 remains elusive." (PMID 31783569, 2019). "Transcription factor GLI1 is an effecter of Hedgehog (HH) signalling and activated in a broad spectrum of cancers." (PMID 30675521, 2019).
cancer (continued). "New Gli1 inhibitors, with improved drug-like properties and prospects for clinical development, will likely be sought after and embraced by the cancer research and drug development communities." (PMID 31137846, 2019). "Treatment of the breast epithelial cell lines MDA-MB-435, T47D, MDA-MB-231, MCF7 and normal epithelial MCF10AT cells with cyclopamine decreased the expression level of GLI1, but it selectively reduced viability and increased apoptosis in the cancer cells." (PMID 31027259, 2019). "Glioma-associated oncogene 1 (GLI1) is a member of the sonic hedgehog pathway, which is overexpressed in GBM cancer cells." (PMID 31614431, 2019). "Comparative analysis between stably and transiently transfected IL-24 in cancer cells revealed similar inhibitory effects on GLI1 expression." (PMID 31783569, 2019). "When Oxy186 was examined in human cancer cells, we observed significant inhibition of endogenous Gli1 expression in PANC-1, A549, and H2030 cells, which corresponds well with the anti-proliferative effects of Oxy186 detected in these cells." (PMID 31137846, 2019). "Activation of the Hh pathway in cancer cell lines increases the invasiveness and %GLI1 nuclear translocation of cancer cells, and inhibition of the pathway inhibited both." (PMID 31394751, 2019). "Studies have shown that HH signaling regulates the survival and proliferation of various cancer cells through GLI1." (PMID 31783569, 2019). "GLI1 activation is also found in many cancers via both HH signalling-dependent and signalling-independent mechanisms." (PMID 30675521, 2019). "GLI1 enhances cancer stem cell properties by upregulating stem cell markers like OCT4, Nanog, and SOX2." (PMID 31492002, 2019). "Studies have shown that pharmacological and genetic inhibition of GLI1 expression in cancer cells induced increased DNA damage and cell death." (PMID 31783569, 2019). "The findings decipher the importance of the posttranscriptional regulation of GLI1, and advance our understanding of the signal transduction mechanism of Hh pathway and Hh pathway activation-related cancers." (PMID 29662197, 2018). "For example, a previous study indicates that KAT2B induces H3K9Ac on the Gli1 target gene promoters in order to induce cell proliferation in cancer cells." (PMID 30305648, 2018). "Antibody specificity was verified using Western-blot analysis of a Gli1 over-expressed cancer cell line, LNCaP-Gli1." (PMID 29423837, 2018). "This is a distinct feature compared to GLI1 and GLI1ΔN as both those proteins are present in normal and cancer cells." (PMID 30158435, 2018). "Relevance of hedgehog pathway genes in cancer cohort and inhibition of its downstream effector (GLI1) towards metastasis in cell lines are explored in the study." (PMID 29329585, 2018). "Consistent with previous study, Daoy cells possess a fully inducible endogenous Hh pathway and present a valuable cancer model for detailed analysis of physiological Hh/GLI1 signaling." (PMID 29662197, 2018). "In this study, we identified multiple new GLI1 target genes using a combination of different genomic surveys and then subjected them to in‐depth validation in human cancer cell lines." (PMID 30098229, 2018). "In a case study using the immunohistochemistry (IHC) assay, we observed that the protein level of Gli1 was greatly elevated in cancer tissues with high CD90 expression." (PMID 29722127, 2018). "Genetic analysis of frameshift mutation c.821delG in exon 8 of GLI1 in gastric and colorectal cancers has shown that this mutation is more prevalent in CRC than GC and that all mutations have been found in cancers with high microsatellite instability." (PMID 30158435, 2018). "Further, GLI1 is known to regulate proliferation and cell cycle progression, cell survival, migration and invasion, cancer cell stemness and self-renewal, and response to chemotherapy." (PMID 29930746, 2018).